IL6 (interleukin 6)
Diseases named in the same sentence as IL6 in open-access papers (continued):
Sharing a sentence is not in itself a finding about the gene and the disease.
Obesity (continued). "The metabolic effects of obesity are caused by the action of interleukin 6 (IL-6), a cytokine released by adipocytes and macrophages." (PMID 36838411, 2023). "In the present study, familial longevity, in addition to higher robustness and better muscular performance, was also significantly associated with a lower prevalence of obesity and lower levels of inflammation, as measured by Il-6 levels." (PMID 36674289, 2023). "The intracellular contents released by accumulated ACs further trigger an immune response and lead to a release of inflammatory factors, such as TNF-α, IL-1β, and IL-6, which induce the dysfunction of chondrocyte homeostasis in obesity-associated OA." (PMID 37144868, 2023). "The proinflammatory cytokines TNFα, IL1, and IL6 are locally increased in obesity, and cause PTP1B activation and insulin resistance." (PMID 37389126, 2023). "The expression of IL-1β and IL-6, which are involved in chronic inflammation associated with obesity, was also significantly decreased in cells treated with transgenic rice seed extracts." (PMID 37631337, 2023). "According to the literature, one of the possible sites of IL-6 production is the adipose tissue, which is mainly associated with obesity development." (PMID 37534321, 2023). "Dysbiosis also affects the secretion of inflammatory cytokines, and it is known that obesity is associated with high levels of IL-6, TNF-alpha, and C-reactive protein." (PMID 37374323, 2023). "Cardiovascular (CV) risk factors (i.e., obesity, diabetes, hypertension, and atherosclerosis) are associated with the inflammatory pathway mediated by IL-1α, IL-6, and IL-8." (PMID 36982253, 2023). "In models of dietary obesity, increased IL-6 secretion has also been associated with reduced muscle mass; however, in models that use MSG exposure, there is a recurrent reduction in the secretion of this cytokine in animals." (PMID 36902158, 2023). "IL-6 is one of the first identified myokines, and, as far as we know, an increase in IL-6 in the bloodstream is associated with obesity and type 2 diabetes (i.e., insulin resistance)." (PMID 37834132, 2023). "The liver is chronically exposed to TNF-α and IL-6, the two major obesity-associated adipose-derived pro-inflammatory cytokines." (PMID 38313077, 2023). "Obesity is linked to hyperactive adipose tissue that secretes inflammatory adipocytokines, e.g., leptin and interleukin-6 (IL-6), which cause, with prolonged exposure, subacute chronic inflammation and insulin resistance." (PMID 36768831, 2023). "Obesity was associated with an upregulation of the gene expression of the inflammatory markers Mcp-1 (p < 0.01), IL-6 (p < 0.01), IL-10 (p < 0.01) and Tnf-α (p < 0.001), and with an upregulation of the mRNA levels of Nox-1 (p < 0.05) and Ho-1 (p < 0.001)." (PMID 37239868, 2023). "Along with endothelial dysfunction, circulating markers of low-grade inflammation such as hsCRP and IL-6 are often elevated in obesity and T2D and associated with a higher risk of cardiovascular events." (PMID 37592243, 2023). "This study’s main purpose was to reveal the association of adipokines (leptin, adiponectin), hs-CRP, and IL-6 with cardiovascular risk factors (lipid profile, diabetes control, obesity, physical activity) in children and adolescents with T1D." (PMID 36010052, 2022). "In adipocytes of obese people, IL-6, as an adipokine, increase and is associated with obesity, inactivity, and inflammation." (PMID 35250869, 2022). "At the level of gene expression regulation, Meta data analysis showed that the -174G>C polymorphism in the promoter region of IL-6 was associated with obesity." (PMID 36105933, 2022). "Both depression and obesity are associated with increased C-reactive protein, tumour necrosis factor-α, interleukin-1, and interleukin-6 levels." (PMID 36002471, 2022).
Obesity (continued). "In mice fed a high-fat diet, with IL-6 deleted from neurons or astrocytes only, neuron IL-6 null mice display resistance to obesity with reduced levels of insulin resistance and loss of glucose homeostasis." (PMID 35470093, 2022). "In individuals, levels of IL-6, leptin, and resistin show an increase in obesity and are inversely associated with low inflammation but can return with exercise." (PMID 35250869, 2022). "IL-6-deficient mice will be obese due to reduced energy consumption, suggesting that IL-6 can enhance energy metabolism to prevent obesity and insulin resistance." (PMID 36105933, 2022). "The observed elevation of IL6 in association with high vs. low trunk fat is consistent with a pro-inflammatory state and prior evidence from reduction mammoplasty specimens that obesity led to enrichment for a pathway involving IL616." (PMID 35087024, 2022). "In rodent models, deficiency in IL-6, IL-1 type I receptor, and IL-18 resulted in hyperphagia and obesity." (PMID 35911732, 2022). "Low muscle mass and obesity are also associated with several inflammatory cytokines, including interleukin-6, serum insulin-like growth factor-1, and hs-CRP." (PMID 36292469, 2022). "In obesity, high visceral fat is the major site for deposition of (IL)-6, which explain the association between depression, inflammation, metabolic risk factors and cardiovascular diseases." (PMID 35998193, 2022). "Obesity is associated with pro-inflammatory and oxidative stress state due to release of inflammatory substances such as interleukin-6, tumour necrosis factor-α and reactive oxygen species." (PMID 36845247, 2022). "The secretion of adipokines (leptin and adiponectin) and cytokines (C-reactive protein, TNF, IL-6, IL-8) driven by adipose tissue in obesity can alter the expression and secretion of factors associated with angiogenesis in the primary tumor." (PMID 36014894, 2022). "Obesity is associated with gradual adipose tissue infiltration with macrophages that secrete proinflammatory cytokines such as interleukin-6 (IL6) and tumor necrosis factor-α (TNFα)." (PMID 36364884, 2022). "Consistently, Arid5a−/− mice showed reduced IL-6 production; mice with long-term loss of Arid5a developed adult-onset severe obesity." (PMID 36408139, 2022). "They suggested that IL-6 can control obesity-associated inflammation by favoring macrophage polarization towards the M2 phenotype, which acts in the resolution phase of inflammation and in repairing damaged tissues." (PMID 35081143, 2022). "In particular, obesity is associated with an increase of IL6 in the circulation, reinforcing systemic inflammation." (PMID 36010901, 2022). "IL-6 is involved in immune regulation and lipid metabolism, and its high expression is usually associated with obesity and insulin resistance." (PMID 36405693, 2022). "We determined plasmatic levels of three of the best-known pro-inflammatory cytokines (TNF-α, IL-1β and IL-6), whose high concentrations are commonly associated with an underlying inflammatory disorder, including obesity and insulin resistance." (PMID 36358463, 2022). "Coupled with a meta-study of 11 reports of associations between cytokines (such as IL-6), periodontitis, and obesity, a picture of cytokine dysregulation and inflammation in the obese, regardless of co-morbidities, emerges." (PMID 36143948, 2022). "Yet, high levels of tumor necrosis factor-α (TNF-α), interleukin-6 (IL-6), adiponectin and angiotensin II and dysregulated metabolites are associated with obesity-induced kidney injury." (PMID 35054932, 2022). "CRP, IL-6, TNFα, and leptin are found to be elevated in individuals with obesity and are also strongly associated with the development of preeclampsia." (PMID 35348641, 2022). "This study’s purpose was to reveal the association of adipokines (leptin, adiponectin), hs-CRP, and IL-6 with well-known cardiovascular risk factors (lipid profile, diabetes control, obesity, physical activity) in children and adolescents with T1D." (PMID 36010052, 2022).
Obesity (continued). "In a previous study, it was shown that TNF-α and IL-6 were associated with obesity or insulin resistance." (PMID 35737354, 2022). "For example, IL6, a pro-inflammatory factor, is associated with the obesity-induced insulin resistance." (PMID 35715850, 2022). "Obesity is usually associated with an increase in inflammation, and high in situ levels of IL-6 and TNFα, which can aggravate liver injury and weaken the hepatic glucolipid and lipid metabolism." (PMID 35382381, 2022). "Regarding the effect of vitamin D on obesity-associated inflammation, increased serum concentrations of inflammatory cytokines, such as IL-6 and TNFα, have been reported in obese subjects with a vitamin D deficiency." (PMID 36142842, 2022). "Obesity in pregnancy is associated with elevated levels of pro-inflammatory cytokines such as interleukin 6 (IL-6), IL-1β, IL-8, and monocyte chemotactic protein-1 (MCP-1) in both the placenta and in maternal plasma." (PMID 36364776, 2022). "The proposed mechanism displayed that obesity-associated IL-6-induced macrophage polarization recruits lymphocytes via the chemokine ligand/chemokine receptor (CCL-20/CCR 6) axis accelerating CAC formation." (PMID 35276983, 2022). "For example, FABP4 promotes tumour cell progression via the IL-6/STAT3/ALDH1 axis in obesity-associated breast cancer." (PMID 35198079, 2022). "The decrease of TNF-α and IL-6 can alleviate insulin resistance and liver steatosis caused by obesity." (PMID 36079890, 2022). "Obesity was associated with an upregulation in the gene expression of IL-1β (p < 0.05), IL-6 (p < 0.01) and NOX-4 (p < 0.05), and with a downregulation in the mRNA levels of the antioxidant enzymes GPX-3 and SOD-1 (p < 0.01 for both) in aortic tissue." (PMID 36009292, 2022). "As an inflammatory factor associated with obesity, the level of IL-6 is positively correlated with obesity." (PMID 36105933, 2022). "Risk factors for the development of OA include age, obesity, physical injury, and low-grade systemic inflammation where pro-inflammatory mediators such as IL-6 and TNFα can exacerbate cartilage erosion." (PMID 36227956, 2022). "Taken together with our current findings, vitamin D and interleukin-6 signaling explain approximately 50% of the association between obesity and MS susceptibility." (PMID 35386698, 2022). "In a previous study, Theurich and co-authors indicate that obesity-associated inflammation and metabolic disturbances depend on IL-6/Stat 3-dependent formation of a distinct NK population in high-fat diet (HFD)-induced obesity in mice." (PMID 35950602, 2022). "The expression of inflammatory markers as CD68, IL-6, TNFα and lysozyme is increased during obesity and associated with insulin resistance." (PMID 36432612, 2022). "In the light of recorded performances, the authors suggest IL-6 as a surrogate marker of inflammation in children with obesity who are at risk for IR and metabolic syndrome." (PMID 36364954, 2022). "CRP is produced in the liver as an acute phase protein in response to the release of IL-6 by macrophages or adipocytes, and the serum level of IL-6 is associated with long-term health risks in women with obesity and type-2 diabetes mellitus." (PMID 36551953, 2022). "In particular, the IL6 polymorphisms designated as rs1800795 as well, were associated with the risk of developing obesity in Egyptian children." (PMID 36452324, 2022). "We were, therefore, interested if IL-6R deficient mice phenocopy IL-6 deficient mice in diet-induced obesity." (PMID 36387898, 2022). "In East Asia: Asian studies, such as a study of 217 adults, found elevated IL-33 (Th2, pro-allergic factor) in obese patients while a study linked IL-6 polymorphisms, obesity, and osteoporosis risk in elderly Chinese women." (PMID 36143948, 2022).
Obesity (continued). "Recent research suggests that IL-6 secretion caused by anxiety and stress, which can lead to the changes in the fatty inflammation microenvironment, is a main mechanism of obesity." (PMID 35668772, 2022). "The association of adipokines (leptin, adiponectin), hs-CRP, and IL-6 with well-known cardiovascular risk factors (lipid profile, diabetes regulation, obesity, physical activity) in children and adolescents with T1D is this study’s main purpose." (PMID 36010052, 2022). "Of these, IL-6 is particularly implicated in inflammation-driven processes that lead to obesity-related diseases." (PMID 35896539, 2022). "High-sensitivity CRP (hsCRP) - a more sensitive systemic inflammatory marker that indicates increased risk for metabolic complication of obesity is associated with other proinflammatory factors in plasma e.g., IL-6, Th1 and Th17 lymphocytes." (PMID 35873001, 2022). "Recent studies showed that obesity caused by a fatty diet increases the serum levels and intestinal expression of proinflammatory cytokines such as IL-6 and TNF-α, which are also key to the course of IBD." (PMID 36364889, 2022). "Collectively, these results suggest that obesity-associated reduction in miR-193b expression leads to the development of IR by reducing adiponectin expression and increasing IL6 and CCL2 expression." (PMID 36421371, 2022). "The level of the obesity-associated inflammatory factor interleukin-6 (IL-6) was significantly reduced in participants who regularly consumed anthocyanins." (PMID 36501200, 2022). "The increase in IL-6 levels during obesity has been linked to β-cell compensatory insulin hypersecretion as it can act directly on pancreatic β-cells, enhancing glucose-stimulated insulin secretion (GSIS) without affecting insulin content." (PMID 35628332, 2022). "We also analyzed their association with biomarkers of obesity (adiponectin and leptin) and inflammation (interleukin-6 (IL-6) and interleukin (IL-10))." (PMID 35207221, 2022). "Il6-deficient mice have been shown to develop adult-onset obesity with impaired glucose and lipid metabolism." (PMID 36408139, 2022). "C-reactive protein (CRP), interleukin 6 (IL-6) and fibrinogen are associated with obesity and affect vascular structure and endothelial function." (PMID 35013379, 2022). "Obesity predisposes the body to a pro-inflammatory state by adipose tissue releasing inflammatory mediators, such as interleukin 6, which triggers hepatocytes to synthesize and secrete CRP." (PMID 36235852, 2022). "In obesity, circulating IL-6 levels are elevated and are associated with-low grade inflammation and dysregulated metabolism." (PMID 35909571, 2022). "Obesity is associated with inflammatory adipokines including leptin, resistin, lipocain 2, IL-6, TNF-α, IL-1β, and IFN-γ." (PMID 35626330, 2022). "Obesity is characterized by high levels of several proinflammatory markers, including IL-6 and TNF-α, that cause chronic low-grade inflammation." (PMID 35336365, 2022). "One major source of IL-6 is from M1 macrophages in adipose tissue, and IL-6 is potential to be the underlying biological mediator to link obesity and asthma by IL-6 trans-signaling pathway and airway inflammation." (PMID 36253437, 2022). "Obesity-driven increased plasma IL-6 in humans is reported to be associated with aggravated liver steatosis and fibrosis." (PMID 35470093, 2022). "For example, FABP4 facilitates the stemness and aggressiveness of tumour cells via the IL-6/STAT3/ALDH1 axis in obesity-associated breast cancer." (PMID 35198079, 2022). "Studies have confirmed that insufficient sleep is associated with increases in tumor necrosis factor, interleukin 6 and C-reactive protein, which play important roles in obesity." (PMID 34952580, 2021).
Obesity (continued). "The single nucleotide polymorphisms (SNPs) rs1800797 (–597 G/A), rs1800796 (–572 G/C), and rs1800795 (–174 G/C) that are located in the promoter region of IL6, on the other hand, were associated with obesity and metabolic traits in different ethnic groups." (PMID 34201855, 2021). "Adiposity, obesity, and obesity-related inflammatory factors such as leptin and interleukin-6 were found to be associated with RNFL thinning in children affecting all except the temporal quadrant." (PMID 33630879, 2021). "Thirdly, emerging evidence supported that IL-6 was associated with ATM accumulation in obesity as well as lipolysis." (PMID 34504646, 2021). "As mentioned, because it produces oxidative stress and causes inflammatory conditions, obesity is one of the factors that increases the basal levels of IL-6, IL-1β, and fibrinogen and reduces anti-inflammatory markers such as IL-10 and nesfatin-1." (PMID 33997019, 2021). "Given that overweight/obesity is associated with chronic inflammation, plasma levels of a major pro-inflammatory cytokine IL-6 were measured." (PMID 33925459, 2021). "The second reason involves inflammatory factor stimulation, as obesity can cause adipose cells to secrete inflammatory factors, such as C-reactive protein, interleukin 6 (IL-6), IL-10, and tumor necrosis factor (TNF-α)." (PMID 35004287, 2021). "Intermuscular lipids are associated with higher levels of myostatin, IL-6, and macrophages infiltration, observed in subjects with obesity." (PMID 34025446, 2021). "Obesity stimulates the adipose tissues to release inflammatory mediators such as tumor necrosis factor α and interleukin 6, predisposing them to a proinflammatory state and oxidative stress." (PMID 34573003, 2021). "Insulin resistance underlying type-2 diabetes (T2DM) superimposed on obesity is known to elevate plasma levels of inflammatory markers such as IL-6, TNFα." (PMID 33510184, 2021). "Interleukin-6 (IL6) produced in the context of exercise acts in the hypothalamus reducing obesity-associated inflammation and restoring the control of food intake and energy expenditure." (PMID 34465367, 2021). "Our longitudinal analysis supports the association between methylation and IL-6 by providing inferred causation from obesity-associated methylation to IL-6." (PMID 34670603, 2021). "Obesity is a state of chronic inflammation associated with increases in circulating inflammatory cytokines including TNFα and IL-6 in humans." (PMID 33752736, 2021). "Obesity is also associated with an elevated level of pro-inflammatory cytokines and chemokines IL-6, RANTES, and IL-1β and of the hormone leptin, which maintains homeostatic control of AT mass." (PMID 34248964, 2021). "Briefly, our data revealed that, obesity in both sexes, especially in males was associated with high levels of circulating IL-6, clusterin and irisin and worsened the metabolic pattern." (PMID 33905632, 2021). "This study aimed at evaluating the circulating levels of IL-6, clusterin, and irisin in obese subjects of both sexes who had different grades of obesity and examining their sexual dimorphism and their association with insulin resistance." (PMID 33905632, 2021). "Others have shown that, among the inflammatory cytokines associated with obesity (IL-6, TNFα, IL-1β), only maternal IL-6 crosses the placental barrier starting in mid-gestation." (PMID 34168254, 2021). "The increase in adiponectin, an inflammatory adipocytokine, such as TNFα, IL-1β, and IL-6, has a large effect on the renal disorders associated with obesity, causing an increase in the mesangial matrix and inflammation of the renal tubular epithelium." (PMID 34959901, 2021). "Scientific evidence suggests that obesity, in particular chronic visceral adiposity, is associated with inflammatory markers including interleukin-6 (IL-6) and tumor necrosis factor-alpha (TNF-α)." (PMID 34938803, 2021).